KCNJ11 (potassium inwardly rectifying channel subfamily J member 11)
Description:
Inward rectifier potassium channel that forms the pore of ATP-sensitive potassium channels (KATP), regulating potassium permeability as a function of cytoplasmic ATP and ADP concentrations in many different cells. Inward rectifier potassium channels are characterized by a greater tendency to allow potassium to flow into the cell rather than out of it. Their voltage dependence is regulated by the concentration of extracellular potassium; as external potassium is raised, the voltage range of the channel opening shifts to more positive voltages. The inward rectification is mainly due to the blockage of outward current by internal magnesium. Can be blocked by extracellular barium (By similarity). In pancreatic cells, it forms KATP channels with ABCC8/SUR1. Can form cardiac and smooth muscle-type KATP channels with ABCC9.
Synonyms: Kir6.2; BIR; HHF2; IKATP; MODY13; PHHI; PNDM2; TNDM3
Tractability: Small molecule: an approved drug acts on it; a structure with a bound ligand is known; a high-quality ligand is known; it belongs to a druggable protein family. Antibody: its Gene Ontology location is reachable by antibodies, with high confidence; UniProt predicts a signal peptide or a membrane-spanning region. PROTAC: ubiquitination databases record sites on it; its protein half-life has been measured; a small molecule that binds it is known. Other modalities: a drug acting on it is in phase 2 or 3 trials.
Target class: Inwardly rectifying potassium channel; Potassium channels; Voltage-gated ion channel; Ion channel
Chemical probes: GLYBURIDE (high quality), REPAGLINIDE (high quality)
Safety:
Unwanted effects reported when the protein is acted on. In parentheses: how it was acted on, where the effect was seen, and who reports it.
abnormal pulse (activation, acute dosing; pancreas, renal, cardiovascular; source: Lynch et al. (2017))
atrioventricular block (inhibition, acute dosing; pancreas, renal, cardiovascular; source: Lynch et al. (2017))
cardiac arrhythmia (activation, acute dosing; pancreas, renal, cardiovascular; source: Lynch et al. (2017))
cardiac lesions (activation, acute dosing; pancreas, renal, cardiovascular; source: Lynch et al. (2017))
decreased blood glucose (inhibition, acute dosing; pancreas, renal, cardiovascular; source: Lynch et al. (2017))
decreased blood insulin (activation, acute dosing; pancreas, renal, cardiovascular; source: Lynch et al. (2017))
decreased blood pressure (activation, acute dosing; pancreas, renal, cardiovascular; source: Lynch et al. (2017))
decreased convulsions (activation, acute dosing; pancreas, renal, cardiovascular; source: Lynch et al. (2017))
decreased heart rate (inhibition, acute dosing; pancreas, renal, cardiovascular; source: Lynch et al. (2017))
increased blood insulin (inhibition, acute dosing; pancreas, renal, cardiovascular; source: Lynch et al. (2017))
increased heart rate (activation, acute dosing; pancreas, renal, cardiovascular; source: Lynch et al. (2017))
increased urinary sodium excretion (inhibition, acute dosing; pancreas, renal, cardiovascular; source: Lynch et al. (2017))
increased urine excretion (inhibition, acute dosing; pancreas, renal, cardiovascular; source: Lynch et al. (2017))
increased/decreased blood glucose (activation, acute dosing; pancreas, renal, cardiovascular; source: Lynch et al. (2017))
new-onset diabetes after transplantation (NODAT) (source: ClinPGx)
Gene: Protein-coding gene on chromosome 11 (17,365,172 to 17,389,353, reverse strand). Ensembl gene ENSG00000187486.
Subcellular location: Membrane
Pathways (Reactome):
Disease: Defective ABCC8 can cause hypo- and hyper-glycemias; Defective ABCC9 causes CMD10, ATFB12 and Cantu syndrome
Metabolism: Regulation of insulin secretion
Muscle contraction: Ion homeostasis
Neuronal System: ATP sensitive Potassium channels
Transport of small molecules: ABC-family protein mediated transport
Gene Ontology:
Molecular function: ankyrin binding; protein binding; transmembrane transporter binding; voltage-gated monoatomic ion channel activity involved in regulation of presynaptic membrane potential; voltage-gated potassium channel activity; ATP binding; ATP-activated inward rectifier potassium channel activity; ATPase-coupled monoatomic cation transmembrane transporter activity; inward rectifier potassium channel activity; potassium ion binding
Biological process: glucose metabolic process; negative regulation of insulin secretion; nervous system process; potassium ion import across plasma membrane; regulation of insulin secretion; regulation of membrane potential; response to ATP; response to xenobiotic stimulus; potassium ion transmembrane transport; transmembrane transport; inorganic cation import across plasma membrane; potassium ion transport; regulation of presynaptic membrane potential
Cellular component: inward rectifying potassium channel; plasma membrane; T-tubule; cytoplasm; membrane; potassium channel complex
Genetic constraint (gnomAD): Loss-of-function variants: 12 observed, 18.11 expected, observed/expected ratio (o/e) 0.66, 90% interval 0.42 to 1.07. The upper end of that interval is the gene's LOEUF score, 1.07, which puts it in group 4 of 6, group 1 being the genes least tolerant of losing a copy. Missense variants: 386 observed, 573.48 expected, observed/expected ratio (o/e) 0.67, 90% interval 0.62 to 0.73. Synonymous variants: 211 observed, 233.58 expected, observed/expected ratio (o/e) 0.9, 90% interval 0.81 to 1.01.
Gene-disease validity (ClinGen):
ClinGen rates the evidence that KCNJ11 causes each of these diseases.
hyperinsulinemic hypoglycemia, familial, 2 (autosomal recessive): Definitive. Any hyperinsulinemic hypoglycemia in which the cause of the disease is a mutation in the KCNJ11 gene.
monogenic diabetes (autosomal dominant): Definitive. Diabetes mellitus that is caused by mutations in a single gene.
hyperinsulinemic hypoglycemia, familial, 2 (autosomal dominant): Limited.
Homologues: Orthologues: chimpanzee KCNJ11 (99% identical), dog KCNJ11 (97% identical), rat Kcnj11 (96% identical), guinea pig KCNJ11 (96% identical), mouse Kcnj11 (96% identical), pig KCNJ11 (93% identical), tropical clawed frog kcnj21 (75% identical), zebrafish kcnj11 (71% identical), Drosophila melanogaster Irk1 (42% identical), Drosophila melanogaster Irk2 (40% identical), Caenorhabditis elegans irk-2 (38% identical), Caenorhabditis elegans irk-1 (35% identical), and 2 more. Paralogues in human: KCNJ8 (69% identical), KCNJ12 (44% identical), KCNJ18 (44% identical), KCNJ2 (44% identical), KCNJ4 (43% identical), KCNJ6 (43% identical), KCNJ9 (43% identical), KCNJ3 (42% identical), KCNJ14 (41% identical), KCNJ5 (41% identical), KCNJ1 (38% identical), KCNJ16 (35% identical), and 3 more.
Diseases named in the same sentence as KCNJ11 in open-access papers:
KCNJ11 is named in the same sentence as 141 diseases in open-access papers, as found by Europe PMC text mining. Sharing a sentence is not in itself a finding about the gene and the disease. The quoted sentences say what the papers report.
diabetes (170 papers, 2003 to 2026). "We present a case report of an infant diagnosed with a pathogenic de novo variant in KCNJ11 (Potassium Inwardly Rectifying Channel Subfamily J Member 11), associated with both transient and permanent neonatal diabetes." (PMID 42220860, 2026). "Isolated Diabetes: Primarily caused by defects in the functional machinery of the β-cell (e.g., KCNJ11, ABCC8, INS)." (PMID 41614934, 2026). "Several SNPs of the KCNJ11 gene have been detected; among them, rs5219 has been receiving more attention for its association with diabetes." (PMID 40352968, 2025). "The KCNJ11 rs5219 variant has been shown to affect pancreatic β-cell function and implicated in type 2 diabetes mellitus susceptibility." (PMID 40944253, 2025). "A pediatric population of 13 neonatal diabetes subjects due to a KCNJ11 mutation revealed higher rates of sleep difficulties compared to sibling controls." (PMID 41158621, 2025). "In the majority of NDM cases caused by KCNJ11 variants, diabetes will appear within the 3 months of life." (PMID 41169283, 2025). "The differential diagnosis initially considered other causes of neonatal diabetes, including transient neonatal diabetes mellitus (6q24 imprinting abnormalities) and monogenic forms of diabetes (KCNJ11/ABCC8 mutations)." (PMID 41393705, 2025). "The frequency of E23K variants of the KCNJ11 genotypes was significantly higher in subjects with T2DM having a positive family history of diabetes compared to control." (PMID 40352968, 2025). "KCNJ11 gene has more than 200 polymorphisms; six of them, rs5215, rs5210, rs5218, rs5219, rs886288, and rs2285676, are related to diabetes." (PMID 40149317, 2025). "Variants in the potassium channel (ABCC8 or KCNJ11) are often associated with neonatal diabetes, but the onset of diabetes can also occur later in life." (PMID 39511990, 2024). "MODY13 is an autosomal dominant form of diabetes caused by mutations in the KCNJ11 gene, and the pathological basis is the dysfunction of pancreatic beta cells and absolute deficiency of insulin secretion." (PMID 38095268, 2024). "SNPs in the TCF7L2, KCNQ1, and KCNJ11 genes were studied, and the results confirmed that these three SNPs were associated with all types of diabetes studied, including T2DM, GDM, and PTDM." (PMID 37107681, 2023). "This is a rare case of PSIS with liver cirrhosis and diabetes associated with an inactivating KCNJ11 gene mutation." (PMID 38152125, 2023). "We report a rare case of PSIS with tall stature, liver cirrhosis and diabetes, possibly caused by an inactivating KCNJ11 gene mutation." (PMID 38152125, 2023). "We adopted oral glibenclamide suspension (Amglidia) for the early treatment of neonatal diabetes due to an homozygous variant of KCNJ11 gene c.10C>T [p.Arg4Cys] in an extremely preterm infant born at 26 + 2 weeks' of gestational age." (PMID 36873092, 2023). "In neonates or infants with diabetes mellitus, genetic testing is an indispensable diagnostic tool and KCNJ11 variants should be considered." (PMID 37251668, 2023). "A study compared neuropsychological features between adults with permanent neonatal diabetes mellitus (PNDM) caused by KCNJ11 variations and by INS variations (the gene encodes insulin; its variations influence insulin synthesis)." (PMID 35654594, 2022). "They concluded that neonatal diabetes was caused by heterozygous mutations of the KCNJ11, with variable onset and the severity of diabetes." (PMID 36361703, 2022). "The variants found in the ABCC8 and KCNJ11 genes have been published in cases with neonatal diabetes phenotype." (PMID 34440499, 2021). "Sulfonylureas (SU) are a class of drugs that are effective in treating diabetes patients with activating mutations in KCNJ11; furthermore, SU treatment also correlates with some improvement in neurodevelopmental outcomes." (PMID 34732776, 2021).
diabetes (continued). "In individuals with diabetes caused by KCNJ11 mutations the sensitivity of these potassium channels was decreased, thereby reducing insulin secretion in the presence of glucose." (PMID 33594477, 2021). "Rare neonatal forms of diabetes that develop within the first year of life are often caused by mutations in the KCNJ11 gene, which encodes a subunit of the pancreatic potassium channel that tightly regulates insulin secretion by beta cells." (PMID 33594477, 2021). "If a diagnosis of diabetes is made before 6 months of age and genetic screening is undertaken, the identification of mutations in KCNJ11 or ABCC8 provides an alternative therapeutic strategy." (PMID 34566892, 2021). "In our research, several genes, such as ABCC8 and KCNJ11, related to insulin and diabetes and encoding Kir6.2 and SUR1 have also been found in the ceRNA network." (PMID 32906679, 2020). "This study showed an association between rs5219 polymorphism of the KCNJ11 gene and type 2 diabetes mellitus in a sample of the Syrian population." (PMID 31195986, 2019). "Several SNPs of the KCNJ11 gene have been detected, among them, rs5219, which has been receiving more attention for its association with diabetes." (PMID 31195986, 2019). "This study showed that rs5219 polymorphism of the KCNJ11 gene is an important risk factor for type 2 diabetes mellitus in a sample of the Syrian population." (PMID 31195986, 2019). "KCNJ11 mutations cause permanent neonatal diabetes through pancreatic ATP-sensitive potassium channel activation." (PMID 29880308, 2018). "A meta-analysis of the effects of KCNJ11 on diabetes risk, combing results from 48 studies of Caucasian, East Asians and Indians, found that the adjusted odds of incident diabetes OR (95% CI) per risk allele was 1.12 (1.09, 1.16)." (PMID 30169531, 2018). "We describe a novel KCNJ11 gene mutation (p.P254Q) in a patient with neonatal diabetes that subsided at the age of 10 months." (PMID 28943514, 2018). "The significance of KCNJ11 variants on diabetes risk in other cohorts has been evaluated, but these cohorts have primarily been Caucasian or Asian." (PMID 30169531, 2018). "Evaluating a combined cohort of ARIC and JHS participants, we sought to determine if KCNJ11 variants are risk factors for diabetes; and if KCNJ11 variants modify the association between serum K and diabetes risk." (PMID 30169531, 2018). "KCNJ11 mutations result in diabetes by rendering the KATP channel unresponsive to metabolically generated ATP." (PMID 30599002, 2018). "If hyperglycemia were to recur, this patient would be a candidate for oral sulfonylurea therapy as oral sulfonylureas have been shown to result in improved glycemic control in patients with diabetes due to KCNJ11 mutations." (PMID 28766502, 2018). "Prenatal testing is particularly relevant for the optimal management of diabetes in pregnant women with a mutation in one of the genes (KCNJ11 or ABCC8) encoding the potassium channel subunits." (PMID 27477181, 2017). "The association of type 2 diabetes mellitus (T2DM) with the KCNJ11, CDKAL1, SLC30A8, CDKN2B, and FTO genes in the Russian population has not been well studied." (PMID 28717589, 2017). "Our aim was to identify factors associated with successful transfer from insulin to sulfonylureas in patients with permanent neonatal diabetes due to mutations in KCNJ11 (which encodes the inwardly rectifying potassium channel Kir6.2)." (PMID 27033559, 2016). "KCNJ11 rs5219 is known to be associated with Type 2 diabetes, thus suggesting a potential interesting link between visual disturbances and diabetes." (PMID 27535653, 2016).
diabetes (continued). "In 4 cases the age at onset of diabetes was less than 6 months, corresponding to neonatal diabetes form, confirmed later with genetic testing and identification of mutation in KCNJ11 gene." (PMID 27842589, 2016). "The high ranking of tolazamide in the insulin sensitivity, islet cell, and β cell models was based on binding assay results for the ATP-sensitive potassium inwardly rectifying channel (KCNJ11) gene, which is commonly associated with diabetes of genetic origin." (PMID 26978842, 2016). "An integrated and collaborative approach to clinical care is needed to ensure early identification and appropriate management of the complex needs of people with diabetes due to KCNJ11 mutations." (PMID 27086753, 2016). "Transfer from insulin is successful for most KCNJ11 patients and is best predicted by the in vitro response of the specific mutation and the duration of diabetes." (PMID 27033559, 2016). "KATP channel mutations are also associated with diabetes that presents in later life, and a common polymorphism in KCNJ11 (E23K) confers an enhanced risk of type 2 diabetes." (PMID 27118464, 2016). "Activating KCNJ11 mutations are associated with a number of clinical features ranging from isolated diabetes to more severe phenotypes such as developmental delay-epilepsy-neonatal diabetes syndrome." (PMID 26300908, 2015). "Genome-wide association studies (GWAS) have reported that the polymorphism rs5219 of the potassium inwardly rectifying channel, subfamily J, member 11 (KCNJ11) is associated with type 2 diabetes mellitus (T2DM)." (PMID 25573672, 2015). "KCNJ11 has 219 SNPs, six of which have been receiving more attention for their association with diabetes." (PMID 26448950, 2015). "Although a diagnosis of diabetes before 6 months of life is highly suggestive of a genetic cause, in such cases other types of monogenic diabetes (due to mutations in KCNJ11, INS or ABCC8 genes) are more plausible and should be evaluated before MODY2." (PMID 24244580, 2013). "Gain-of-function mutations in either the Kir6.2 (KCNJ11) or SUR1 (ABCC8) subunits of the channel that impair the inhibitory effects of ATP cause a rare genetic form of diabetes that presents shortly after birth (permanent neonatal diabetes mellitus or PNDM)." (PMID 23626843, 2013). "Only one mutation (p.Glu227Lys in KCNJ11) co-segregated with diabetes in the family (with a LOD-score of 3.68)." (PMID 22701567, 2012). "We describe a 3-year-old girl with permanent neonatal diabetes mellitus with a mutation in the KCNJ11 gene (R201H), who was successfully transferred from subcutaneous insulin to oral glibenclamide, with a marked improvement in glycemic control." (PMID 20220270, 2010). "Considerable data support heritable defects in β-cell function leading to increased diabetes susceptibility, but to date only the glutamine to lysine variant at position 23 in the β-cell potassium channel gene (KCNJ11 E23K) is widely accepted." (PMID 16869959, 2006). "KCNJ11 is associated with diabetes and cardiac conduction defects." (PMID 40149317, 2025). "Although the patient’s mother carried the same inactivating KCNJ11 mutation and had diabetes, it is unknown if she had abnormal glucose levels during pregnancy." (PMID 38152125, 2023). "The remaining four cases had inherited the pathogenic variant from their mothers, two of whom (both harboring KCNJ11 variants) were diagnosed with diabetes at 3 months of age and had been treated with insulin until the genetic diagnosis in their children (aged 29 and 35)." (PMID 36398453, 2023). "Mutations in KCNJ11 inhibit the ability of ATP to regulate the potassium channel while enhancing stimulatory magnesium, altering insulin secretion and ultimately causing diabetes." (PMID 36128718, 2022). "Subsequently, only one mutation (p.Glu227Lys in KCNJ11) co-segregated with diabetes in the family." (PMID 36361703, 2022). "Mutations in KCNJ11 can cause diabetes and neurocognitive dysfunction." (PMID 34732776, 2021).